SMAD3 (SMAD family member 3)
Diseases named in the same sentence as SMAD3 in open-access papers (continued):
Sharing a sentence is not in itself a finding about the gene and the disease.
breast carcinoma (continued). "This study first establishes the interactome of Smad3 in breast cancer cells and identifies ZNF8 as a novel Smad3 cofactor." (PMID 39225541, 2024). "Jun family transcription factors are involved in the TGF-β–induced invasive properties of breast cancer cells: JunB cooperates with Smad3 to induce WNT7B and enhance tumor invasiveness." (PMID 38569937, 2024). "Various other non-canonical TGF-β1 signal transducers, such as GSK-3β and NF-κB, also suppress the expression of Smad3 (canonical TGF-β1 signaling) in breast cancer." (PMID 38675493, 2024). "Based on SMAD3 gene expression, patients with breast cancer were divided into the high-expression group and the low-expression group." (PMID 38514720, 2024). "For example, Transcriptional activity of SMAD2/SMAD3:SMAD4 heterotrimer involved in the degradation of SKI/SKIL, thus causing malignant transformation in breast cancer." (PMID 38652712, 2024). "Then, TRIM24-SMAD3 complex is recruited to chromatin, which enhances SMAD3 activation and immune response-related cytokine expression, ultimately promotes breast cancer stemness and enhances metastasis in triple-negative breast cancer." (PMID 39160596, 2024). "It has been reported that CEBPA (C/EBPα) is a Smad3-repressed target during TGFβ-induced EMT in human breast cancer." (PMID 36785790, 2023). "Activation of SMAD3 in the TGF-β pathway is predominant in breast cancer, and a large number of post-translational modifications of SMAD3 play a role in the development of breast cancer." (PMID 37685308, 2023). "To determine the relevance of TGF-β signaling in the context of the tumor-secreted factors of invasive breast cancer cell lines, we set out to assess SMAD3 and ERK1/2 activation in neutrophils treated with M4 TCM over time." (PMID 37682817, 2023). "The TRIM24-SMAD3 complex is further recruited to chromatin, which enhances SMAD3 activation and immune response-related cytokine expression, thereby promoting enhanced breast cancer stemness, MDSC (myeloid-derived suppressor cell) recruitment, and metastasis." (PMID 37953273, 2023). "It has been reported that RBPMS inhibited breast cancer cell growth and migration by interacting with c-Fos or SMAD3 in cultured cells and in mouse xenograft models." (PMID 37704624, 2023). "EZH2-mediated SMAD3 K53/K333 methylation was upregulated and correlated with SMAD3 hyperactivation in breast cancer, promoted tumor metastasis, and was predictive of poor survival outcomes." (PMID 35085106, 2022). "Consistent with this notion, it has been reported that WWOX can inhibit the TGFβ signaling pathway in breast cancer cells by directly binding to SMAD3." (PMID 36572673, 2022). "There is also evidence that TGF-β/SMAD3 can regulate IL-8 and PTHrP, which can stimulate bone metastasis of breast cancer cells." (PMID 35413833, 2022). "In order to experimentally distinguish Smad2 and Smad3 target sites, Smad2 and Smad3 fusion proteins were transfected into the breast cancer cell line MDA-MB-231 in a native cis-regulatory environment as BAC transgenes." (PMID 35858839, 2022). "In this study, we first validated a LAP-tagged R-Smad system that enables identification of Smad2- and Smad3-specific binding sites in a breast cancer cell line." (PMID 35858839, 2022). "During breast cancer pulmonary metastasis in mice, TGFβ signaling stabilizes Smad3 necessary for metastasis in a Bcl-3-dependent manner." (PMID 35681213, 2022). "Further analyses using the GEPIA2 and TIMER2.0 databases revealed that NOLC1 was positively correlated with stemness-related genes, including MYC, ALDH18A1, ALDH1A1, SMAD2, SMAD3, etc., in both all breast cancer and TNBC." (PMID 35174077, 2022). "Taking the results together, it would be of interest to examine the contribution of TGF-β/SMAD3 signaling dynamics during lymph node metastasis of breast cancer cells containing the CAGA12-dynGFP reporter by performing long-term intravital imaging." (PMID 35626109, 2022).
breast carcinoma (continued). "Treatment with the TβRII inhibitor LY2109761 also rescued the effect of HTR1A knockdown on TβRII/p‐Smad3 expression and the migration ability of breast cancer cells." (PMID 35199941, 2022). "We also showed that patients with breast cancer who had lung or lymphatic metastases had higher SMAD3 methylation levels." (PMID 35085106, 2022). "To further investigate the relationship between EZH2 and SMAD3 methylation and phosphorylation in breast cancer, we performed IHC staining assays on breast carcinoma samples." (PMID 35085106, 2022). "Higher expression of SMAD3 correlated with poorer OS of breast cancer patients compared to those with lower SMAD3 expression." (PMID 36123344, 2022). "Bcl-3 has been shown to stabilize the transforming growth factor-β (TGFβ)-activated transcription factor, Smad3, in conjunction with metastatic spread of mouse mammary tumors." (PMID 35681213, 2022). "For example, TGF-β-induced SMAD3/4 mediates acetylation or methylation at H3K9 during EMT in breast cancer cells, thus activating genes like SNAIL or repressing genes like E-cadherin, respectively." (PMID 35127527, 2021). "Previously, we demonstrated that CCL2/CCR2 chemokine signaling in breast cancer cell lines regulated growth and invasion through p42/44MAPK and SMAD3 dependent mechanisms." (PMID 33888841, 2021). "In breast cancers, Smad3 controls Nox4, and in pancreatic cancers, Nox4 delivers ROS for the EMT phenotype switch." (PMID 34947978, 2021). "Next, we employed the mouse 4T1 murine mammary carcinoma metastasis model to determine the effects of SMAD3 acetylation on the recruitment of MDSCs in vivo." (PMID 34392614, 2021). "The next pathway, ESR1, which was mutated in breast cancer, received microenvironment factor S100A4 to regulate TF ETS1 and SMAD3 through signaling transduction proteins ZNF516, PIK3R1, IDH1, and AKT1." (PMID 33802957, 2021). "To further demonstrate the critical role of the proinflammatory cytokine secretion by breast cancer cells in SMAD3‐mediated tumor metastasis, we generated IL‐6 KO 4T1 cells and found that IL‐6 KO inhibited SMAD3‐2KQ‐induced MDSCs recruitment." (PMID 34392614, 2021). "In sum, we confirmed that tRF-17-79MP9PP significantly suppresses cells malignant activities as a new tumor-suppressor through the THBS1/TGF-β1/Smad3 axis in breast cancer." (PMID 33912465, 2021). "Another study revealed that blocking the function of Smad3 in the MCF-10A-derived breast cancer cells led to suppression of metastatic foci in lungs of mice." (PMID 33809098, 2021). "Mechanistically, cyclin E-CDK2 and cyclin D1-CDK4/6 complexes can suppress Smad3 through its phosphorylation, and the suppression of Smad3 releases the Rb1-E2F blockade and restore cell cycle arrest in breast cancer cells." (PMID 34123801, 2021). "The altered protein levels of Smad2 and Smad3 were observed in several type of cancers, including breast cancer, compared to normal mammary epithelial cells." (PMID 33809098, 2021). "We showed that similarly to other studies using breast cancer-derived cells, the blockage between both signaling pathways is because E2 decreases the Smad2 and Smad3 proteins expression." (PMID 33925221, 2021). "Activated SMAD3 upregulates immune‐related cytokines, leading to enhanced breast cancer stem‐like cell properties, myeloid‐derived suppressor cell (MDSC) recruitment, and triple‐negative breast cancer (TNBC) metastasis." (PMID 34392614, 2021). "Recently, miR-5590-3p has been reported as a negative regulator of TGF-β/SMAD3 signaling pathway, by inhibiting SMAD3 in breast cancer." (PMID 33758603, 2021). "Taken together, these data suggested that tRF-17-79MP9PP can suppress the TGF-β1/Smad3 signaling pathway by targeting THBS1 in breast cancer cells." (PMID 33912465, 2021).
breast carcinoma (continued). "Together, these results demonstrated that LAE inhibits the cell migration of ER− breast cancer cells likely via suppressing the phosphorylation of TGF-β1/Erk1/2 as well as TGF-β1/SMAD3 signals." (PMID 33602253, 2021). "Previous studies have shown that SMAD3 regulates mammary tumor growth, invasion and metastasis in mouse models." (PMID 33888841, 2021). "Pin1 also interacts with Smad3 to drive oncogenic TGFβ signalling and promote breast cancer progression." (PMID 32347623, 2020). "ChIP-Seq results obtained from GSE130364 also revealed that SMAD3 bound the promoter region of p21 in breast cancer cells." (PMID 32140069, 2020). "To check the methylation level of SMAD3 in other cancers, we performed a DNA methylation analysis in esophageal, lung, endometrial, and breast cancer." (PMID 33036415, 2020). "TrkB expression is significantly increased in tissues obtained from breast cancer patients relative to normal breast tissue, with TrkB strongly associating with SMAD2, SMAD3, and SMAD4." (PMID 32340410, 2020). "Smad3 phosphorylation strongly correlates with Med15 levels in breast and lung cancer tissues; together, they potentiate metastasis of breast cancer cells." (PMID 32463833, 2020). "CSMD1 coprecipitated SMAD3 in breast cancer cells and human adipocytes, and a reciprocal immunoprecipitation further confirmed the interaction." (PMID 32701512, 2020). "In previous studies, we demonstrated an important role for p42/44MAPK and SMAD3 in CCL2/CCR2 breast cancer cell motility." (PMID 31208996, 2019). "Targeting miR489 as well as Smad3 can be of substantial use in treatment of HER2-positive breast cancer." (PMID 31083383, 2019). "For example, Ets-1 cooperates with Smad3 to stimulate the expression of parathyroid hormone-related protein (PTHrP) in breast cancer cells." (PMID 31189885, 2019). "Similar to the function of TGFβ, BMP receptor II/Smad3 contributes to telomerase inhibition and telomere shortening in human breast cancer cells, leading to replicative senescence." (PMID 30627420, 2019). "Recent investigations indicated that elevated expression of miR-489 blocked cell growth, invasion and EMT by targeting Shp2 in hypopharyngeal carcinoma, SMAD3 in breast cancer, AKT3 in ovarian cancer, and Dek in ovarian cancer, as well as muscle stem cells." (PMID 31083383, 2019). "For example, pAMPK prevented TGF-β-mediated phosphoactivation of SMAD2 and/or SMAD3 in vascular smooth muscle and breast cancer cells." (PMID 31640193, 2019). "In human breast cancer cells, TGFβ negatively mediates telomerase activity through its downstream effector, Smad3." (PMID 30627420, 2019). "On the contrary, Cbl-b binds to Smad3 and promotes breast cancer proliferation by inhibiting the TGF-signaling pathway." (PMID 29940895, 2018). "The TGF‐β‐induced EGFR expression was more strongly inhibited by the double suppression of Smad3 and Sp1 expression than by the single‐Sp1 or single‐Smad3 siRNA‐transfected breast cancer cells." (PMID 29215776, 2018). "Consistently, knockdown of Smad3 in breast cancer cells also decreases the upregulated EGFR expression induced by TGF‐β treatment." (PMID 29215776, 2018). "In this study, we found that the EGFR expression was significantly lower in Smad3‐silenced breast cancer cells treated with MTM than in the cells with single‐silenced Smad3." (PMID 29215776, 2018). "To study the relevance of the GPR50/TβRI complex on cell proliferation and tumor development we choose the MDA-MB-231 breast cancer cell line in which we were able to recapitulate the spontaneous Smad2 and Smad3 phosphorylation in the presence of GPR50." (PMID 29572483, 2018). "We found the TGFβ effects on COX-2 expression and cancer stemness to be Smad3 dependent in basal breast cancer." (PMID 28054666, 2017).
breast carcinoma (continued). "In breast cancer, Cbl-b binds to the proline rich region of Smad3 and prevents the protein from translocating into the nucleus to inhibit the transcription of tumor suppressor genes downstream of the TGF-β pathway, including p21Cip1 and p15INK4b." (PMID 28915662, 2017). "Here we report that the cytokine bone morphogenetic protein-7 (BMP7) induces the hTERT gene repression in a BMPRII receptor- and Smad3-dependent manner in human breast cancer cells." (PMID 27696331, 2017). "Of these preselected genes, only SMAD3 expression correlates with breast cancer cell shape; specifically, SMAD3 expression correlates with cell W/L." (PMID 27864353, 2017). "We found COX-2 to be required for TGFβ/Smad3-mediated regulation of breast cancer stemness in basal-like TNBCs." (PMID 28054666, 2017). "Then weconsidered the protein level of Bcl-3 and Smad3 in some breast cancer cellswith different metastasis potential." (PMID 27906182, 2016). "Our findings support the notion that Smad3 has important tumor suppressor function for breast cancer." (PMID 27588495, 2016). "Snail1 is a cofactor for Smad3/4 during TGF-β-induced EMT, and a strong correlation was also found between loss of CAR and E-cadherin and nuclear co-expression of Snail1 and Smad3/4 in breast cancer." (PMID 27548154, 2016). "Previous studies based on cell culture and xenograft animal models suggest that Smad3 has tumor suppressor function for breast cancer during early stages of tumorigenesis." (PMID 27588495, 2016). "Previous xenograft experiments showing Smad3 tumor suppressor function for breast cancer used the MCF10CA1h cell line, which contains an oncogenic H-Ras mutation." (PMID 27588495, 2016). "For example, miR-489 has been shown to directly target other oncogenes such as Shp2 in HSCC, SMAD3 in breast cancer, AKT3 in ovarian cancer and Dek in mouse muscle stem cells." (PMID 26918448, 2016). "Rescue experiments in vitro further confirm thatBcl-3-depletion induced decreases of Smad3 protein in breast cancer cellscontribute to reduced migration and invasion ability in vitro andlung metastasis in vivo." (PMID 27906182, 2016). "Researchers have investigated the specific functions of Smad2 and Smad3 inTGFβ-induced signaling in breast cancer cells invitro and in a mouse model of breast cancer metastasis." (PMID 27906182, 2016). "Here we reportthat Bcl-3 functions as a critical regulator of TGFβ signaling bystabilizing Smad3 to promote the pulmonary metastasis of breast cancer." (PMID 27906182, 2016). "Notably, Smad3 overexpression only partially rescued the deficiency caused byBcl-3 loss, suggesting that other mechanisms might be involved in the regulationof the pulmonary metastasis of breast cancer by Bcl-3." (PMID 27906182, 2016). "For breast cancer, Cbl-b binds to Smad3 through its proline-rich region and prevents the protein from transferring into the nucleus to inhibit the transcription of tumor suppressor genes downstream of the TGF-β pathway, including p21Cip1 and p15INK4b." (PMID 27494897, 2016). "Smad2 and Smad3 play differential roles in executing TGFβ1 signaling resulting in either suppression or promotion of breast cancer progression." (PMID 27641158, 2016). "In our study, we found that Bcl-3 regulated breast cancerpulmonary metastasis in breast cancer cells by modulating TGFβsignaling via the stabilization of Smad3 and other metastasis-related proteinssuch as ID1 (see discussion below)." (PMID 27906182, 2016). "A previous study showed that Cbl-b directly binded to Smad3 through a proline-rich motif, thereby preventing Smad3 from interacting with Smad4 and blocking nuclear translocation of Smad3 in breast cancer cells." (PMID 27494897, 2016). "In this report, we show that DMBA (7,12-dimethylbenz[a]anthracene), a chemical carcinogen, induces mammary tumor formation at a significantly higher frequency in the Smad3 heterozygous mice than in the Smad3 wild type mice." (PMID 27588495, 2016).
breast carcinoma (continued). "This is the first genetic evidence showing that Smad3 inhibits mammary tumor formation in a mouse model." (PMID 27588495, 2016). "We show in this study that DMBA-induced mammary tumor formation is accelerated in the Smad3+/− mice compared to the Smad3+/+ mice." (PMID 27588495, 2016). "Taken together, these findings suggest that hypoxia induced miR-191 increases breast cancer cell migration through TGFβ2 induction in a SMAD3-dependent manner." (PMID 25867965, 2015). "In terms of its breast cancer-promoting properties, Smad3/4 transcription factors activated by TGF-β1 bind to the promoter region of MDM2 to increase its protein expression." (PMID 25278993, 2014). "HMGB1–TLR2 signaling via signal transducer and activator of transcription factor 3 (STAT3) and Smad3 activation enhances breast cancer stem cell self-renewal and increases breast cancer metastasis." (PMID 24723911, 2014). "We had previously shown that TGF-β can induce differentiation in this breast cancer model, and here we demonstrated that this effect is mediated by Smad3." (PMID 24890385, 2014). "Having identified a set of core TGF-β/Smad3 target genes in the breast cancer model system using the ChIP-chip approach, we next determined which of these were specifically important for the tumor suppressive functions of TGF-β by assessing gene expression." (PMID 24890385, 2014). "It has been demonstrated that TGFβ induces COX2 expression and subsequent PGE2 production and that up-regulated COX2 inhibits Smad3 activation during breast cancer progression." (PMID 25327961, 2014). "We have generated a TGF-β/Smad3-driven gene expression signature that specifically captures the tumor-suppressive effects of TGF-β in ER+ breast cancer." (PMID 24890385, 2014). "The present study found that the signaling pathway of POGLUT1 in BT474 human breast cancer cells involves a POGLUT1/Smad3/p16/CDK/pRb pathway, and the signal is increased by TGF-β1." (PMID 25009645, 2014). "The data presented here suggest that cAMP promotes TGFβ/Smad3-mediated expression in breast cancer cells by upregulating the expression of the TGFβ receptor TβRI." (PMID 23349840, 2013). "We found that as few as 1 MSC per 300 breast cancer cells was able to induce Smad3 and CREB phosphorylation in breast cancer cells." (PMID 23349840, 2013). "Collectively, these data indicate that active TGFβ/Smad3 signaling is associated with high p21 and p/CAF protein expression levels and significantly correlates with lymph node metastasis in breast cancer." (PMID 22995475, 2012). "The loss or reduction of BRCA1 expression, moreover, significantly reduces the TGF-beta induced activation of SMAD3 in breast cancer cells." (PMID 22646717, 2012). "Taken together, our results demonstrate that p21 is both a direct transcriptional target of TGFβ and a co-stimulatory factor of Smad3 in regulation of pro-invasive genes in breast cancer cells." (PMID 22995475, 2012). "Together, our findings identified p21 and p/CAF as critical regulators of cell migration and invasion downstream of TGFβ/Smad3 pathway in advanced breast cancer." (PMID 22995475, 2012). "Immunohistochemical analysis of tissue arrays from breast cancer patients revealed a significant correlation between active TGFβ/Smad3 signaling and high expression levels of both p21 and p/CAF in lymph node-positive invasive ductal carcinomas." (PMID 22995475, 2012). "In our studies, we identified a novel role for p21 in the transcriptional regulation of TGFβ/Smad3 signaling through the interaction of p21 and Smad3 in invasive breast cancer cells." (PMID 22995475, 2012).